RPRM (reprimo, TP53 dependent G2 arrest mediator homolog)
Description:
Seems to induce cell cycle arrest by inhibiting CDK1 activity and nuclear translocation of the CDC2 cyclin B1 complex (By similarity).
Synonyms: FLJ90327; REPRIMO
Tractability: Antibody: UniProt predicts a signal peptide or a membrane-spanning region.
Gene: Protein-coding gene on chromosome 2 (153,477,338 to 153,478,762, reverse strand). Ensembl gene ENSG00000177519.
Subcellular location: Cytoplasm; Membrane
Gene Ontology:
Molecular function: protein binding
Biological process: regulation of cell cycle; regulation of mitotic cell cycle
Cellular component: cytoplasm; membrane
Genetic constraint (gnomAD): Loss-of-function variants: 3 observed, 5.06 expected, observed/expected ratio (o/e) 0.59, 90% interval 0.27 to 1.48. That is too few expected variants to judge how well the gene tolerates losing a copy. Missense variants: 135 observed, 165.2 expected, observed/expected ratio (o/e) 0.82, 90% interval 0.71 to 0.94. Synonymous variants: 70 observed, 75.61 expected, observed/expected ratio (o/e) 0.93, 90% interval 0.76 to 1.13.
Homologues: Orthologues: chimpanzee RPRM (100% identical), macaque RPRM (100% identical), pig RPRM (100% identical), rabbit RPRM (98% identical), rat Rprm (98% identical), mouse Rprm (97% identical), guinea pig RPRM (96% identical), dog RPRM (84% identical), tropical clawed frog rprm (75% identical), zebrafish rprma (72% identical), zebrafish rprmb (66% identical). Paralogues in human: RPRML (55% identical).
Diseases named in the same sentence as RPRM in open-access papers:
RPRM is named in the same sentence as 20 diseases in open-access papers, as found by Europe PMC text mining. Sharing a sentence is not in itself a finding about the gene and the disease. The quoted sentences say what the papers report.
gastric cancer (7 papers, 2016 to 2023). A primary or metastatic malignant neoplasm involving the stomach. "Our results, by demonstrating the epigenetic-associated silencing of cancer-related genes (ZNF793 and RPRM), provide a molecular mechanism to explain the increased risk of IM progressing to the intestinal type of gastric cancer." (PMID 34199386, 2021). "A gain of methylation was observed for ZNF793 and RPRM genes in the intestinal type of gastric cancer compared with their normal paired counterpart (p < 0.005)." (PMID 34199386, 2021). "The promoter methylation and decreased expression of RPRM in gastric cancer is consistent with the role of RPRM as a tumor suppressor gene." (PMID 29312555, 2017). "Reprimo (RPRM) is a tumor-suppressor gene that has been found to be involved in the progression of a variety of malignant tumors such as pituitary tumors, gastric cancer, etc., and thus may serve as a biomarker for early cancer detection." (PMID 38069378, 2023). "Reprimo (RPRM) is a tumor suppressor gene involved in the development of gastric cancer." (PMID 31540371, 2019). "Importantly, in humans, RPRM is a gene which expression is lost in many human gastrointestinal malignancies and serves as a potential biomarker for non-invasive detection of gastric cancer (reviewed in the following section)." (PMID 29941787, 2018). "Consequently, restoring the expression of RPRM by the use of demethylating agents, such as 5-aza-cytidine has confirmed that the expression of RPRM gene is regulated by DNA methylation in gastric cancer cells." (PMID 29941787, 2018). "However, the regulation of RPRM gene expression by DNA methylation in gastric cancer is not well understood." (PMID 29312555, 2017).
pituitary tumor (2 papers, 2015 to 2023). A benign or malignant neoplasm affecting the pituitary gland. "In addition, RPRM has been proposed as a putative tumor suppressor gene in renal cell carcinoma and pituitary tumors." (PMID 25954972, 2015).
Anxiety (1 paper, 2023). Intense feelings of nervousness, tension, or panic often arise in response to interpersonal stresses. "We found that RPRM knockout did not significantly affect the locomotor activity and anxiety level in mice before and after WBI." (PMID 38069378, 2023).
breast tumor (1 paper, 2017).
cognitive decline (1 paper, 2023). "However, it was noted that RPRM deletion alone showed a tendency to cause cognitive decline in mice." (PMID 38069378, 2023). "Additionally, the tendency of cognitive decline in RPRM KO mice coincided with the decreasing trend in their neurogenesis." (PMID 38069378, 2023).
Cognitive impairment (1 paper, 2023). Abnormal cognition is characterized by deficits in thinking, reasoning, or remembering. "RPRM deletion dramatically mitigates radiation-induced neuroinflammation, which in turn contributes to the attenuation of radiation-induced neurogenesis inhibition and cognitive impairment in RPRM KO mice." (PMID 38069378, 2023). "To confirm the potential role of RPRM in RIBI, we further investigated how RPRM deletion would affect late-delayed RIBI, i.e., radiation-induced cognitive impairment." (PMID 38069378, 2023).
lymph node metastasis (1 paper, 2015). "Progression from stage I GC to stages II-IV (p = 0.006) and lymph node metastasis (p = 0.037) were significantly associated with loss of expression of RPRM gene protein product." (PMID 25954972, 2015).
ovarian carcinoma (1 paper, 2021). A malignant neoplasm originating from the surface ovarian epithelium. "Thereby, our findings identified cooperation of DDX3X and RPRM to promote translation of PHGDH transcript in cisplatin-resistant ovarian cancer cells." (PMID 34178629, 2021).
tumor (20 papers, 2014 to 2025). "The loss of RPRM enhanced the tumor formation in the in vivo model, confirming the role of RPRM as a tumor suppressor gene in GC." (PMID 36360266, 2022). "In addition, we generated RPRM gene-knockout cells and studied the effects of the RPRM deficiency on tumor formation by inoculating these cells in mice." (PMID 29312555, 2017). "In this study, we developed a novel fluorescence-based real-time PCR assay based on the methylation of the promoter region of RPRM, a well-established tumor suppressor gene and recognized biomarker for GC." (PMID 40244164, 2025). "In other neoplasm similar results have been obtain confirming the role of DNA methylation as the main mechanisms of regulation of RPRM gene expression." (PMID 29941787, 2018). "In humans, who have only RPRM and RPRM-Like (RPRML), the RPRM gene appears to be involved in tumor suppression in tumors of the gastrointestinal tract as well as in multiple other organs." (PMID 29941787, 2018). "Its most characterized member, RPRM, which duplicated to give rise rprma and rprmb in the fish lineage, is known to act as a tumor-suppressor gene in mammalian models." (PMID 29636669, 2018). "RPRM is a potential tumor suppressor gene constituted by a unique exon of 327 bp located at 2q23.3, which encodes a glycosylated protein of 109 amino acids frequently found in the cytoplasm." (PMID 28809778, 2017). "Taken together, these data suggest that RPRM is involved in decreased cell migration and invasion in vitro, acting as a potential tumor suppressor gene in the MDA-MB-231 cell line." (PMID 26796959, 2016). "Accordingly with this loss of RPRM expression in the progression of GC, our functional assays (colony formation and anchorage-independent growth) also proposed a putative tumor suppressor role for RPRM in GC." (PMID 25954972, 2015). "The aim of this study was to evaluate the epigenetic silencing of RPRM gene by promoter methylation and its tumor suppressor function in GC cell lines." (PMID 25954972, 2015). "In summary, our data suggest that epigenetic silencing of RPRM gene by promoter methylation is associated with loss of RPRM expression and accordingly, functional assays proposed a putative tumor suppressor role of RPRM in GC." (PMID 25954972, 2015). "As the loss of RPRM expression was associated in GC and mainly with the progression from stage I to II-IV, a tumor suppressor role of RPRM might be plausible." (PMID 25954972, 2015). "However only 25% (5/20) of tumor samples showed expression of RPRM gene protein product." (PMID 25954972, 2015). "Interestingly, also a number of oncogenes is up regulated by E2 (MERTK, RET and its ligand ARTN), and several (putative) tumor suppressor genes are down regulated by E2 (BLNK, LATS2, RPRM) that are not, or less, regulated by EGF." (PMID 24758408, 2014).
cancer (5 papers, 2017 to 2023). A tumor composed of atypical neoplastic, often pleomorphic cells that invade other tissues. "As other intronless gene families, such as JUN and FOX, the RPRM gene family is often implicated in cancer through their overrepresentation in cell growth and proliferation." (PMID 29941787, 2018). "Methylation at the ZNF793 and RPRM genes is initiated during IM, and reaches the highest levels in cancer samples." (PMID 34199386, 2021). "Two epigenetically regulated genes in cancer, RPRM and ZNF793, consistently showed increased methylation in intestinal metaplasia with respect to earlier precursor lesions." (PMID 34199386, 2021). "At experimental and clinical levels, only the RPRM gene has been examined in terms of biological functions and significance in human cancer." (PMID 29941787, 2018). "Furthermore, the regulation of expression and the translational applications of the RPRM gene family in cancer medicine need to be further elucidated, along with a potential role in other pathologies." (PMID 29941787, 2018). "Genes whose median expression was below the threshold in more than half of the cancer types were common in cohorts A and B (ADGRB1, IGF1, RPRM, TP53AIP1)." (PMID 36964217, 2023).
RPRM also shares sentences with these, for which no sentence is quoted: acute myeloid leukemia (1 paper); breast carcinoma (1); colon cancer (1); connective tissue disorder (1); diverticulosis (1); gastrointestinal disease (1); lung carcinoma (1); pancreatic tumors (1); renal cell carcinoma (1); schizophrenia (1).